RPL7 (ribosomal protein L7)
Description:
Component of the large ribosomal subunit. The ribosome is a large ribonucleoprotein complex responsible for the synthesis of proteins in the cell. Binds to G-rich structures in 28S rRNA and in mRNAs. Plays a regulatory role in the translation apparatus; inhibits cell-free translation of mRNAs.
Synonyms: humL7-1; L7; uL30
Tractability: Small molecule: an approved drug acts on it; a structure with a bound ligand is known; a high-quality ligand is known. PROTAC: ubiquitination databases record sites on it; its protein half-life has been measured; a small molecule that binds it is known. Other modalities: a drug acting on it is in phase 2 or 3 trials.
Target class: Other cytosolic protein
Gene: Protein-coding gene on chromosome 8 (73,290,242 to 73,295,789, reverse strand). Ensembl gene ENSG00000147604.
Subcellular location: Cytoplasm
Subcellular location (Human Protein Atlas): Cytosol; Endoplasmic reticulum; Nucleoli
Pathways (Reactome):
Metabolism of proteins: Eukaryotic Translation Termination; Formation of a pool of free 40S subunits; GTP hydrolysis and joining of the 60S ribosomal subunit; L13a-mediated translational silencing of Ceruloplasmin expression; PELO:HBS1L and ABCE1 dissociate a ribosome on a non-stop mRNA; Peptide chain elongation; Ribosome Quality Control (RQC) complex extracts and degrades nascent peptide; SRP-dependent cotranslational protein targeting to membrane; ZNF598 and the Ribosome-associated Quality Trigger (RQT) complex dissociate a ribosome stalled on a no-go mRNA
Metabolism of RNA: Major pathway of rRNA processing in the nucleolus and cytosol; Nonsense Mediated Decay (NMD) enhanced by the Exon Junction Complex (EJC); Nonsense Mediated Decay (NMD) independent of the Exon Junction Complex (EJC)
Cellular responses to stimuli: Response of EIF2AK4 (GCN2) to amino acid deficiency
Developmental Biology: Regulation of expression of SLITs and ROBOs
Disease: Viral mRNA Translation
Metabolism: Selenocysteine synthesis
Gene Ontology:
Molecular function: DNA binding; identical protein binding; mRNA binding; protein binding; RNA binding; structural constituent of ribosome
Biological process: ribosomal large subunit biogenesis; rRNA processing; cytoplasmic translation; maturation of LSU-rRNA from tricistronic rRNA transcript (SSU-rRNA, 5.8S rRNA, LSU-rRNA); negative regulation of myoblast fusion; spermatogenesis; striated muscle contraction; translation
Cellular component: cytoplasm; cytosol; cytosolic large ribosomal subunit; cytosolic ribosome; focal adhesion; membrane; nucleolus; nucleus; postsynaptic density; ribonucleoprotein complex
Genetic constraint (gnomAD): Loss-of-function variants: 0 observed, 22.83 expected, observed/expected ratio (o/e) 0, 90% interval 0 to 0.13. The upper end of that interval is the gene's LOEUF score, 0.13, which puts it in group 1 of 6, group 1 being the genes least tolerant of losing a copy. Missense variants: 161 observed, 210.42 expected, observed/expected ratio (o/e) 0.77, 90% interval 0.67 to 0.87. Synonymous variants: 73 observed, 72.44 expected, observed/expected ratio (o/e) 1.01, 90% interval 0.83 to 1.22.
Homologues: Orthologues: chimpanzee RPL7 (100% identical), macaque RPL7 (98% identical), pig RPL7 (97% identical), tropical clawed frog rpl7 (78% identical), zebrafish rpl7 (78% identical), Drosophila melanogaster RpL7 (59% identical), Caenorhabditis elegans rpl-7 (55% identical), rat Rpl7-ps3 (30% identical). Paralogues in human: RPL7L1 (44% identical).
Diseases named in the same sentence as RPL7 in open-access papers:
RPL7 is named in the same sentence as 33 diseases in open-access papers, as found by Europe PMC text mining. Sharing a sentence is not in itself a finding about the gene and the disease. The quoted sentences say what the papers report.
systemic lupus erythematosus (4 papers, 2005 to 2022). An autoimmune multi-organ disease typically associated with vasculopathy and autoantibody production. "Researchers implicate autoantigens, including RPL7, RPL31, RPL14, and RPL9, in the regulation of diseases such as systemic lupus erythematosus, rheumatoid arthritis, and systemic sclerosis." (PMID 35432523, 2022). "The RPL7 gene was rated second by the CGC application mainly because of the keywords 'autoimmune', 'lupus' and 'erythematosus'." (PMID 15899035, 2005).
brucellosis (3 papers, 2014 to 2020). Brucellosis is a bacterial infection that spreads from animals to people via unpasteurized dairy products or by exposure to contaminated animal products or infected animals. "The ribosomal protein L7/L12 has been previously identified as immunodominant and protective antigen of Brucella abortus, the causative of Brucellosis, another major worldwide disease." (PMID 26148026, 2015). "The present study uses the highly immunogenic Brucella ribosomal protein L7/L12 in a Salmonella secretion platform as a live attenuated vaccine for brucellosis." (PMID 31973749, 2020). "In this study, we first developed recombinant influenza A viruses of the subtypes Н5N1 and H1N1 expressing Brucella ribosomal protein L7/L12 or Omp16, and then demonstrated that these vaccines could be used as new candidates for a brucellosis vaccine." (PMID 24716528, 2014).
ovarian carcinoma (3 papers, 2021 to 2025). A malignant neoplasm originating from the surface ovarian epithelium. "Our results demonstrated Ribosomal protein L7 (RPL7), as a hub gene in exosomes driven from ovarian cancer stem cells." (PMID 39891297, 2025). "Notably, expression levels of RPS6, RPL12, CTNNB1, RPL7, RPS2, and CALM3 did not have any impact on the survival of ovarian cancer patients." (PMID 39309198, 2024).
viral infection (3 papers, 2019 to 2024). "RPL18 and RPL7 have been also found in siRNA screens performed with yellow fever and West Nile virus." (PMID 31040842, 2019).
cervical cancer (2 papers, 2023 to 2025). A primary or metastatic malignant neoplasm involving the cervix. "For instance, in cervical cancers, how FLCs interact with proteins like RPL7, RPS3, H1-5, and H1-6, and the exact process of FLCs promoting sarcoma proliferation, are not yet fully understood." (PMID 40806736, 2025).
colorectal cancer (2 papers, 2021 to 2024). A primary or metastatic malignant neoplasm that affects the colon or rectum. "To this end, we knocked down RPS3, RPS6 and RPS20 as well as RPL7 in human HCT116 colorectal cancer cells that are either WT or deficient for p5343." (PMID 39609413, 2024). "Whilst little is known about the involvement of RPL7 in lung cancer, it is involved in microsatellite instability in colorectal cancer." (PMID 33777753, 2021).
Sepsis (2 papers, 2025). Sepsis is defined as life-threatening organ dysfunction caused by a dysregulated host response to infection. "Significant expression of the ribophagy-specific receptor NUFIP1 and autophagy-associated protein LC-3B was observed in CD4+ T lymphocytes after sepsis, with a corresponding decrease in the expression of ribosomal self-proteins ribosomal protein L7 (RPL7), RPL23, and RPL26." (PMID 40995563, 2025).
cholera (1 paper, 2025). "The aliphatic indices of cholera-vaccine, PADRE vaccine, the RS09-vaccine, and the 50S ribosomal protein L7/12 ranged from 65.88 to 77.81, indicating high thermostability, whereas the aliphatic index of the beta-defensin-vaccine was 35.21, indicating low thermostability." (PMID 40806344, 2025).
colon cancer (1 paper, 2021). "Previous studies suggested that Rpl7 could affect trophoblast differentiation, and is abnormally expressed in colon cancer and other diseases." (PMID 34066653, 2021).
colorectum carcinoma (1 paper, 2013). "Ribosomal protein expression has been shown to be differentially regulated in human colorectum carcinoma, in which ribosomal protein L7 has a neuroendocrine function." (PMID 24137416, 2013).
COVID-19 (1 paper, 2024). A disease caused by infection with severe acute respiratory syndrome coronavirus 2. "Also, spec_24h mRNAs were enriched in 12 KEGG terms such as Coronavirus disease-COVID-19, Ribosome, MAPK signaling pathway, Cytokine-cytokine receptor interaction, Focal adhesion, involving genes such as Rpl7, Rpl3, Rpl5, Rpl4, Rps15a." (PMID 38622534, 2024).
diffuse astrocytoma (1 paper, 2018). A low-grade (WHO grade II) astrocytic neoplasm. "Considering the similarity of fetal and tumor at the differential state level, we speculate that in the diffuse astrocytoma, the expression level of RPL7 and RPL8 may be quite different from the other two glioma subtypes." (PMID 30322114, 2018). "Apart from XIST, the two homologues, namely, RPL7 and RPL8, have also been predicted to have quantitative patterns in diffuse astrocytoma." (PMID 30322114, 2018).
endometriosis (1 paper, 2025). The growth of functional endometrial tissue in anatomic sites outside the uterine body. "Thus, given these low levels of expression, Cxcr2 expression in IgG-treated minced endometrial tissue was normalized relative to ribosomal RpL7 gene expression to enable comparisons between treatment and endometriosis groups." (PMID 39836475, 2025).
senile dementia (1 paper, 2021). "Recent studies have shown that RPL7 and RPL23A are differentially expressed in senile dementia and may be potential biomarkers." (PMID 33859672, 2021).
tuberculosis (1 paper, 2018). A chronic, recurrent infection caused by the bacterium Mycobacterium tuberculosis. "The 60S ribosomal protein L7 pseudogene was reported to have reduced expression in cattle with tuberculosis." (PMID 30309336, 2018).
infection (16 papers, 2010 to 2025). The state of being infected such as from the introduction of a foreign agent such as serum, vaccine, antigenic substance or organism. "The stability ranking at different developmental stages associated with infection of PWN was as the following: TER > RPL7 > RPS5 > Zdhhc15 > EF1-γ > RPL18 > Tmub1 > SNX6 > ATPase > TFAM > α-TUB > EIF > TPI > COX7." (PMID 35547586, 2022). "TER and RPL7 were stable reference genes at different developmental stages associated with infection of PWN." (PMID 35547586, 2022). "We concluded that RPL7 and TER were suitable reference genes at different developmental stages associated with infection of PWN." (PMID 35547586, 2022). "Under experimental conditions of this study, RPL7 and TER were suitable reference genes at different developmental stages associated with infection of PWN." (PMID 35547586, 2022). "For different developmental stages associated with infection of PWN and pupae treated with PWN, two conditions had similar results that RPS5, RPL18, and RPL7 were identified as the most stable genes, but α-TUB, COX7, EIF, and SNX6 were poor stable genes." (PMID 35547586, 2022). "TER, RPL7, and RPS5 were the optimal reference genes at different developmental stages associated with infection of PWN." (PMID 35547586, 2022). "Among all samples, RPL7 and RPS5 were the most stable reference genes, similar with the results found in the sample sets of different developmental stages associated with infection of PWN and all PWN treatment conditions." (PMID 35547586, 2022). "This is the first report exploring reference gene expression during a NNV infection in halibut, and amongst the genes tested especially RPL7 was shown to be a good candidate, but also EF1A1 and HPRT1." (PMID 20459764, 2010). "Thus, RPL7 might influence a shutdown of the mRNA translation system in the advanced stages of cellular infection, leading to the cessation of the viability of the insect’s tissues." (PMID 38076451, 2023).
tumor (6 papers, 2014 to 2026). "Finally, we identified 4 putative tumor-derived Igλ-associated proteins including ribosomal protein L7 (RPL7), ribosomal protein S3 (RPS3), histone cluster 1, H1b (H1-5), histone cluster 1, H1t (H1-6)." (PMID 37784026, 2023). "After analysis of a series of bioinformatics data of tumor-derived Igλ, we obtained four potential tumor-derived Igλ-interacting proteins, namely RPL7, RPS3, H1-5, and H1-6, using Co-IP combined with LC–MS/MS." (PMID 37784026, 2023). "The efficacy of a 50S ribosomal protein L7/L12 (rplL) from Mycobacterium tuberculosis Rv0652, as an immunoadjuvant for DC-based tumor immunotherapy, and its capacity for inducing DC maturation was investigated." (PMID 25102137, 2014). "The interaction of tumor-derived Igλ with RPL7 suggests that tumor-derived Igλ may be involved in DNA damage repair." (PMID 37784026, 2023). "In addition, RPL7 directly interacts with RPS3, while H1-5 or H1-6 has no direct interaction with other three tumor-derived Igλ-interacting proteins respectively." (PMID 37784026, 2023).
cancer (3 papers, 2006 to 2025). A tumor composed of atypical neoplastic, often pleomorphic cells that invade other tissues. "These included RPL6, RPL7, RPL18A, RPS2, EIF3E, EIF3J, and UBA52, reflecting the elevated protein synthesis demands of cancer cells." (PMID 41228302, 2025). "Genes encoding components of the translation machinery, the mitochondrial ribosomal protein MRPL15 and cytosolic ribosomal proteins RPL7 and RPS20, are located in this region, highlighting the need for enhanced translation in cancer cells." (PMID 16982006, 2006).
neurodegenerative disease (2 papers, 2020 to 2022). A disorder of the central nervous system characterized by gradual and progressive loss of neural tissue and neurologic function. "HTT, neurofilament heavy chain (NF‐H), Tau (MAPT), FUS, TDP‐43, HNRNPA1, HNRNPD, RPL7 and actin (ACTB, found aggregated in Hirano bodies in several neurodegenerative diseases; Hirano, 1994), were selectively aggregated upon RNase A/T1 treatment of human neuronal lysates." (PMID 32945072, 2020).
connective tissue diseases (1 paper, 2021). "RPL7 is a Protein Coding gene which is associated with systemic autoimmune diseases, such as SLE and other connective tissue diseases." (PMID 34521416, 2021).
RPL7 also shares sentences with these, for which no sentence is quoted: rheumatoid arthritis (2 papers); anemia (1); autoimmune disease (1); glioma (1); HCMV infection (1); hepatoma (1); lung carcinoma (1); metabolic syndrome (1); myopathies (1); neuroblastoma (1); prostate carcinoma (1); sarcoma (1); systemic sclerosis (1).